IFITM1 (interferon induced transmembrane protein 1)
Diseases named in the same sentence as IFITM1 in open-access papers (continued):
Sharing a sentence is not in itself a finding about the gene and the disease.
COVID-19 (continued). "In this study, we evaluated the expression of IFITM1 and IFITM3 in peripheral leukocytes from healthy controls and individuals with severe pandemic influenza A(H1N1) or coronavirus disease 2019 (COVID-19)." (PMID 35708622, 2022). "Moreover, IFITM1 is down-regulated in the COVID-19 group (either mild or severe) compared with the healthy group, while RPS15A is down-regulated in the severe group compared with the healthy group." (PMID 35601483, 2022). "Among the identified gene signatures, IFITM2, IFITM1, H3F3B, SAT1, and S100A8 gene signatures were highly associated with neutrophils, while CCL8, CCL3, CCL2, KLF6, and SPP1 were associated with macrophage cluster-1 in severe-COVID-19 patients." (PMID 33138195, 2020). "Consistently, genes (e.g., ISG15, IFITM1/2/3, OAS3 and IFIT1/2/3) associated with the IFN-response pathway, especially for IFN-I response, were significantly upregulated in COVID-19 associated acute necrotizing encephalopathy compared with healthy donors and other COVID-19 groups." (PMID 37848421, 2023). "When analyzed further, COVID-19 acute necrotizing encephalopathy patients also had various ISGs upregulated (e.g., ISG15, IF27 and IFITM1/2/3 etc.), consistent with our GO analysis." (PMID 37848421, 2023). "IFN-related genes, such as ISG15, IFITM1 and GBP4, were also downregulated in B_naive and B_activated of severe compared to moderate COVID-19." (PMID 37095364, 2023). "Similarly, other genes involved in type I interferon signaling (IFITM1 and IFITM3) and cellular activation (UBC, FOS, and DUSP1) were increased in a severity-dependent manner, suggesting an enhanced EF B-cell activity associated with an overt inflammatory condition in severe COVID-19." (PMID 35899045, 2022). "Global neutrophil expression aligned with neutrophil state-specific markers, such as interferon response genes (IFITM1, RSAD2, IFI6 and ISG10), being more highly expressed in COVID-19 neutrophils." (PMID 34782790, 2022). "This analysis revealed a positive correlation between the levels of expression of IFITM1 and IFITM3, even when their overall expression patterns looked contrasting when compared with HC and COVID-19 patients." (PMID 35708622, 2022). "IFITM1 and other ISG genes are considered potential targets for the development of drugs for COVID-19 treatment." (PMID 35928229, 2022). "Accordingly, MKs undergoing shortened differentiation and expressing anti-viral IFITM1 and IFITM3 RNA as a sign of viral sensing were enriched in the circulation of deadly COVID-19." (PMID 35708858, 2022). "Previous work has shown increased expression of IFITM3 in platelets from COVID-19 patients; our dataset includes the differential abundance of ISG15 and IFITM1, reinforcing the importance of platelets in antiviral response." (PMID 35842415, 2022). "We found that placental mRNA expression of IFITM1 and IFITM3 was upregulated in participants with severe disease when compared to asymptomatic/mild COVID-19-positive pregnant women." (PMID 34257394, 2021). "When we analyzed DEGs, severe COVID-19 was characterized by up-regulation of various ISGs, including ISG15, IFITM1/2/3, and ISG20." (PMID 32651212, 2020). "Classical monocytes in severe COVID-19 were found to be accompanied by the IFN-I response that was characterized by the up-regulation of various interferon-stimulating genes (ISGs), including ISG15, IFITM1/2/3, ISG20, IFI27, and MX1 when compared to mild COVID-19." (PMID 36159873, 2022). "Hence, we analyzed the relative mRNA expression of IFITM1 and IFITM3 in our cohort of patients with severe influenza A(H1N1), using HC and individuals with severe COVID-19 as reference." (PMID 35708622, 2022). "While the expression of IFITM1 and IFITM3 was prominent in the villous core and perivascular regions, IFITM3 was also localized to trophoblasts, and was upregulated in women with severe COVID-19." (PMID 34257394, 2021).
COVID-19 (continued). "Although the analysis was limited to only two patients without individual cell-type resolution, in genome browser, up-regulation of IFITM1, ISG15, and JAK3 and down-regulation of RPS18 were observed commonly in post-mortem COVID-19 lung tissues and classical monocytes of severe COVID-19." (PMID 32651212, 2020). "COVID-19 neutrophils preferentially transitioned from the apex of the trajectory, which was an immature state (TOP2A-expressing) to an IFNactive state characterized by IFITM1, IFITM2 and IFI6 expression (clusters 1–4 and 5; Online Atlas) and activation of type I IFN signaling pathways." (PMID 34782790, 2022). "In module 2, enhanced expression of glycolysis (GAPDH and TPI1) and IFN response (IFITM2, IFITM1, IFITM3, IFNGR2, and ISG20) genes in human COVID-19 patients, particularly severely ill patients, may promote the differentiation of unswitched memory B cells into plasmablasts." (PMID 33936072, 2021). "In fact, an ROC analysis showed that IFITM1, but not IFITM3, distinguishes severe pandemic influenza A(H1N1) from COVID-19." (PMID 35708622, 2022). "Regarding COVID-19, our findings in COVID-19 critically ill patients showed the expression of IFITM3, but not IFITM1." (PMID 35708622, 2022). "Interestingly, IFITM1 and IFITM3 expression levels were not correlated with most clinical characteristics and comorbidities of COVID-19 patients and did not influence in-hospital complications or mortality." (PMID 35708622, 2022). "The expression of inflammatory genes typically involved in MK anti-viral response, such as IFITM1 and IFTIM3, together with the non-classical MK differentiation pathway that we observed support the development of an emergency megakaryopoiesis in severe COVID-19, avoiding the MEP commitment." (PMID 35708858, 2022).
breast carcinoma (26 papers, 2014 to 2024). "The down-regulation of IFITM1 has been linked to both low-grade diffuse astrocytomas and breast cancer." (PMID 26300991, 2015). "Indeed, IFITM1 is associated with an increased microvessel density in lung and breast cancer." (PMID 36466909, 2022). "Ifitm1 (Interferon Induced Transmembrane Protein 1; UniProt P13164) has been directly tied to aggressiveness of breast cancer cells." (PMID 38193115, 2024). "And the overexpression of IFITM1 was confirmed to be correlated with the progressing of several cancers including ovarian cancer, breast cancer, oral cancer, lymphoma, and leukemia." (PMID 33688507, 2021). "Enhanced interferon-alpha (IFNα) signaling is upregulated in breast cancers resistant to AIs, which drives expression of a key regulator of survival, interferon-induced transmembrane protein 1 (IFITM1)." (PMID 34680281, 2021). "Recently, our lab identified overexpression of multiple ISGs in AI-resistant breast cancer including interferon-induced transmembrane protein 1 (IFITM1), which is critical for regulating survival of acquired AI-resistant breast cancer cells." (PMID 34680281, 2021). "Several studies reported overexpression of IFITM1 in some types of tumors, such as colorectal, gastrointestinal and breast cancers 49,50." (PMID 32626514, 2020). "IFITM1 has been shown to be overexpressed in several types of cancers, including colorectal, gastrointestinal, head and neck, and breast cancers, and its overexpression positively correlates with tumor progression and increased invasiveness." (PMID 26897526, 2016). "While our studies identified a panel of ISGs that were constitutively overexpressed in our AI-resistant breast cancer cells, IFITM1 was the most functionally significant of the ISGs in the resistant cells." (PMID 25588716, 2015). "Clinical data indicated that IFITM1 was constitutively overexpressed in 36 out of 40 AI-resistant breast tumor samples and it was overexpressed in AI-resistant breast cancer cells approximately 20- to 30-fold at the mRNA and protein level." (PMID 25588716, 2015). "Overall, these results demonstrate that constitutive overexpression of ISGs enhances the progression of AI-resistant breast cancer and that suppression of IFITM1 and other ISGs sensitizes AI-resistant cells to estrogen-induced cell death." (PMID 25588716, 2015). "To investigate the role of IFITM1 in breast cancer progression, we examined the influence of IFITM1 knockdown on migration and invasion of AI-resistant MCF-7:5C breast cancer cells." (PMID 25588716, 2015). "Provance and their colleagues found that the IFITM1 could be affected by crosstalk between the NF-κB and interferon-alpha and regulated breast cancer progression." (PMID 37063301, 2023). "Interestingly, IFITM1 overexpression has been shown to enhance the aggressive phenotype of SUM149 inflammatory breast cancer cells in a signal transducer and activator of transcription 2 (STAT2)-dependent manner." (PMID 36230929, 2022). "In addition, STAT1 and ERα directly interact and regulate a key interferon-stimulated gene, IFITM1, in AI-resistant breast cancer cells." (PMID 34680281, 2021). "Estrogen, the JAK/STAT inhibitor, Ruxolitinib, or inhibitors of other ERα and JAK/STAT coactivators could effectively treat AI-resistant patients or IFITM1-expressing breast cancer in combination." (PMID 34680281, 2021). "We should note that the ability of E2 to induce cell death in AI-resistant breast cancer cells has previously been reported by our laboratory; however, this is the first study to show that suppression of IFITM1 enhances E2-induced cell death in AI resistant breast cancer cells." (PMID 25588716, 2015). "In our study, we demonstrated that several ISGs including IFITM1, STAT1 and PLSCR1 and their encoded proteins are constitutively overexpressed in AI-resistant breast cancer cells and AI-resistant tumors and that their overexpression provides a survival advantage in the resistant cells." (PMID 25588716, 2015).
breast carcinoma (continued). "Furthermore, we showed that targeting ISGs, especially IFITM1, sensitized AI-resistant breast cancer cells to estrogen-induced cell death and it blocked the ability of these cells to migrate and invade." (PMID 25588716, 2015). "To understand better the role of the interferon signaling pathway in AI-resistant breast cancer we measured the basal expression of two well-known interferon stimulated proteins, IFITM1 and PLSCR1, in AI-resistant MCF-7:5C breast cancer cells and AI-sensitive MCF-7 and T47D cells." (PMID 25588716, 2015). "A nomogram was constructed using 7 IRGs, including GPR132, IFITM1, IL12B, IL18, IRF7, KCNMB2, and TACR1, to predict the 1-, 2-, and 3-year survival of breast cancer patients." (PMID 37304237, 2023). "For breast cancer, we find out that HSPA2A, RNASE1, CLIC6, and IFITM1 are highly expressed in some specific groups." (PMID 33133130, 2020). "In breast cancer cells, upregulation of PITX2 promotes letrozole resistance via transcriptional activation of IFITM1 signaling." (PMID 31043858, 2019). "Real-time PCR and Western blot analyses were used to assess mRNA and protein levels of IFITM1, PLSCR1, STAT1, STAT2, and IRF-7 in AI-resistant MCF-7:5C breast cancer cells and AI-sensitive MCF-7 and T47D cells." (PMID 25588716, 2015). "In the present study, we investigated the functional role of IFITM1 and PLSCR1 in AI-resistant breast cancer." (PMID 25588716, 2015). "We found that IFITM1 and PLSCR1 were constitutively overexpressed in AI-resistant MCF-7:5C breast cancer cells and AI-resistant tumors and that knockdown of IFITM1 significantly reduced their ability to proliferate, invade, and migrate." (PMID 25588716, 2015). "Next, we investigated the clinical significance of IFITM1 and PLSCR1 expression in AI-resistant (recurrence) breast cancer by performing IHC staining on normal breast tissue, primary breast tumors (N = 40) and AI-resistant recurrence breast tumors (N = 40)." (PMID 25588716, 2015). "Interestingly, IFITM1 and IFITM3 levels positively correlate with the ER and PR status of breast cancer tissues." (PMID 36466909, 2022). "In addition to their connection with DNA-damaging agents, IFITM1 and IFITM3 are positively correlated with the development of aromatase inhibitor resistance in breast cancer cells." (PMID 36466909, 2022). "For breast cancer, we select five essential genes, such as CTSA, HSPA2, RNASE1, CLIC6, IFITM1." (PMID 33133130, 2020). "We found that IFITM1 and PLSCR1 were constitutively overexpressed in AI-resistant MCF-7:5C breast cancer cells and AI-resistant tumors and that siRNA knockdown of IFITM1 significantly inhibited the ability of the resistant cells to proliferate, migrate, and invade." (PMID 25588716, 2015). "To determine the functional significance of IFITM1 and PLSCR1 in AI-resistant MCF-7:5C breast cancer cells, we transiently transfected MCF-7:5C cells with siRNA targeting IFITM1 or PLSCR1 and we assessed the effect of their knockdown on cell proliferation, cell death and cell cycle progression." (PMID 25588716, 2015). "Using an engineered metastatic niche, we identified a 9‐gene signature (Dhx9, Dusp12, Fhl1, Ifitm1, Ndufs1, Pja2, Slc1a3, Soga1, Spon2) that successfully delineated metastatic breast cancer from nonmetastatic breast cancers including an invasive cell line without metastatic potential." (PMID 38193115, 2024). "Indeed, increased expression of IFITM1, a well-known ISG, has been shown to correlate with disease progression, resistance to endocrine therapy and chemotherapy, and worse overall prognosis in patients with gastrointestinal, colorectal, and breast cancers." (PMID 26897526, 2016).
breast carcinoma (continued). "In this study, we measured IFITM1 expression in three IBC cell lines—SUM149, SUM190, and MDA-IBC-3—and in a non-IBC breast cancer cell line, MCF-7." (PMID 26897526, 2016). "Previous studies have reported that IFITM1 and PLSCR1 exert both antiproliferative and proliferative effects in different types of cancer cells; however, their functional significance in AI-resistant breast cancer cells is not known." (PMID 25588716, 2015).
colorectal cancer (18 papers, 2012 to 2026). A primary or metastatic malignant neoplasm that affects the colon or rectum. "This is consistent with our findings that higher expression of IFITM1 is associated with an increased risk of colorectal cancer." (PMID 41595533, 2026). "It was also demonstrated that IFITM1 was associated with cancer progression and metastasis in many cancers including glioma, colorectal cancer, head and neck cancer, and NSCLC." (PMID 32668617, 2020). "Interferon-induced transmembrane protein 1 (IFITM1) has been shown to be implicated in multiple cancers, yet little is known about biological significance of IFITM1 in colorectal cancer." (PMID 27852071, 2016). "We report that IFITM1 is essential for the migration and invasion of colorectal cancer and is also associated with a poor prognosis of the disease." (PMID 27852071, 2016). "Collectively, these results suggest that IFITM1 is essential for the migration of colorectal cancer cells and is implicated in maintaining EMT signature through CAV1." (PMID 27852071, 2016). "To determine the biological relevance of the results obtained from colorectal cancer cell lines, we analyzed the expression of IFITM1 and its association with patient survival rate using colorectal cancer patient-derived samples." (PMID 27852071, 2016). "Several studies have shown the involvement of IFITM1 in the progression of colorectal cancer and resected gastric and esophageal adenocarcinomas." (PMID 39273214, 2024). "The roles of IFITM1 has been summarized that it involves in gallbladder carcinoma, esophageal adenocarcinoma, colorectal cancer, and gastric cancer." (PMID 38729966, 2024). "circIFITM1 originated from the second exon of IFITM1 gene and was stably expressed in human colorectal cancer cell lines." (PMID 35783017, 2022). "Transfection of LoVo and HT-29 colorectal cancer cells with small interfering RNA (siRNA) targeting IFITM1 reduced migration and invasion capacities of these cells in a wound-healing assay, whereas overexpression of IFITM1 enhanced these capacities." (PMID 34290978, 2021). "Other published studies have also connected IFITM1 to the progression of colorectal cancer, showing that it modifies the proliferating, invasive, and metastatic capability of CRC cell lines." (PMID 34609520, 2021). "Consistent with our observation, a previous study in colorectal cancer demonstrated that IFITM1 expression was significantly higher in liver metastatic regions than in normal and tumor regions of patient-derived samples." (PMID 32668617, 2020). "It was reported that IFITM1 is involved in the invasion and/or metastasis of various cancers including glioma, colorectal cancer, ovarian cancer, head and neck cancer, and NSCLC." (PMID 32668617, 2020). "Recently, increasing studies have shown overexpression of IFITM1 in a variety of cancers, such lung, gastrointestinal and colorectal cancers." (PMID 31781559, 2019). "Total RNA was isolated from control cells or IFITM1-depleted colorectal cancer cell lines, and RT-qPCR was performed to analyze the expression of several genes associated with epithelial and mesenchymal characteristics." (PMID 27852071, 2016). "IFITM1 protein level was also decreased in IFITM1 shRNA-transduced colorectal cancer cell lines (SW620, HT29 and HCT116), compared to that in the control cells." (PMID 27852071, 2016). "Colorectal cancer cell lines were transduced with either nonsense control (shLacZ) or IFITM1 shRNA (shIFITM1) and selected with puromycin." (PMID 27852071, 2016). "To determine the functional importance of IFITM1 in colorectal cancer, we used shRNA to inhibit the expression of IFITM1 in cancer cell lines." (PMID 27852071, 2016). "Here, we attempted to study the critical role of IFITM1 in colorectal cancer development and progression using patient-derived samples as well as several colorectal cancer cell lines." (PMID 27852071, 2016).